FABP4 (fatty acid binding protein 4)
Diseases named in the same sentence as FABP4 in open-access papers (continued):
Sharing a sentence is not in itself a finding about the gene and the disease.
acute myeloid leukemia (3 papers, 2020 to 2025). Acute myeloid leukemia (AML) is a group of neoplasms arising from precursor cells committed to the myeloid cell-line differentiation. "In addition, FABP4 promoted aggressive acute myeloid leukemia (AML) in obesity by enhancing aberrant DNA methyltransferase 1 (DNMT1)-dependent DNA methylation of tumor cells." (PMID 33339340, 2020).
cholangiocarcinoma (3 papers, 2017 to 2025). A carcinoma that arises from the intrahepatic biliary tree (intrahepatic cholangiocarcinoma) or from the junction, or adjacent to the junction, of the right and left hepatic ducts (hilar cholangiocarcinoma). "Our previous study reported that FABP4 derived from adipocytes in the microenvironment could promote the metastasis of cholangiocarcinoma by entering into cancer cells." (PMID 34056002, 2021). "There is a positive feedback loop between FABP4 and PPARG in promoting fatty acid uptake and oxidation in lymph node metastasis of cholangiocarcinoma." (PMID 40604951, 2025). "There is a positive feedback loop between FABP4 and PPARG in facilitating fatty acid uptake and oxidation in cholangiocarcinoma lymph node metastasis." (PMID 40604951, 2025).
cognitive decline (3 papers, 2022 to 2023). "Results showed that HFD-fed FABP4 knockout mice have a hippocampal transcriptome consistent with neuroprotection, including associations with decreased proinflammatory signaling, ER stress, apoptosis, and cognitive decline." (PMID 36834799, 2023). "As many targets of WNT/β-Catenin were found to be unchanged in this study, further work is necessary to determine the mechanism and role of WNT/β-Catenin signaling in the alleviation of HFD-induced neuroinflammation and cognitive decline caused by FABP4 knockout." (PMID 36834799, 2023). "Our data support that loss of FABP4 prevents cognitive decline in vivo." (PMID 35457171, 2022). "We have previously shown that obese FABP4 knockout mice exhibit decreased neuroinflammation and cognitive decline." (PMID 36834799, 2023). "We hypothesized that the link between lipid metabolism and inflammation indicates a role for FABP4 in regulating high fat diet (HFD)-induced cognitive decline." (PMID 36834799, 2023). "We hypothesized that the link between lipid metabolism and inflammation indicates a role for FABP4 in regulating HFD-induced cognitive decline." (PMID 36834799, 2023). "We hypothesized that knockout of FABP4 attenuates HFD-induced cognitive decline via reduced neuroinflammation characterized by microgliosis and inflammatory cytokine expression." (PMID 35457171, 2022). "As there is much supporting evidence that the WNT/β-Catenin pathway is neuroprotective against cognitive decline, our study suggests a role for WNT/β-Catenin in the FABP4 knockout-induced alleviation of cognitive decline." (PMID 36834799, 2023). "Collectively, our work shows that FABP4 represents a potential target in alleviating HFD-induced neuroinflammation and cognitive decline and suggests a role for WNT/β-Catenin in this protection." (PMID 36834799, 2023). "We and others have shown that knockout of FABP4 leads to an alleviation of HFD-induced peripheral and central inflammation, insulin insensitivity, and cognitive decline." (PMID 36834799, 2023). "The HFD-fed FABP4 knockout model has revealed an altered hippocampal transcriptome that is shown to have changes in metabolic pathways and be neuroprotective against HFD-induced neuroinflammation and cognitive decline." (PMID 36834799, 2023).
Cognitive impairment (3 papers, 2023 to 2025). Abnormal cognition is characterized by deficits in thinking, reasoning, or remembering. "Moreover, Morris water maze (MWM) assessments were conducted to evaluate whether microglial FABP4 modulation could mitigate ICH-induced cognitive deficits." (PMID 41204337, 2025). "In a fatty acid binding protein 4 (FABP4)-knockout (KO) model, our laboratory has shown that mice fed a high-fat diet (HFD) exhibited resistance to hippocampal neuroinflammation and cognitive impairment." (PMID 41515969, 2025).
hypothyroidism (3 papers, 2019 to 2024). Abnormally low levels of thyroid hormone. "It evaluated the association between FABP‐4 serum levels with demographics, liver function tests and lipid profile in hypothyroidism patients compared to healthy control." (PMID 39527497, 2024). "The association of serum FABP4 and other biochemical‐related parameters is important to determine complications of hypothyroidism." (PMID 39527497, 2024). "The data suggest that FABP‐4 could potentially be a superior diagnostic indicator for hypothyroidism when contrasted with a control." (PMID 39527497, 2024). "The data suggest that FABP‐4 could potentially be a superior diagnostic indicator for hypothyroidism when contrasted with a control cohort in future studies." (PMID 39527497, 2024). "Serum FABP4 levels of patients with hypothyroidism and control group were 5.92 ± 1.13 (1.28–8.67) and 5.51 ± 0.96 (1.37–7.65) pg/mL, respectively." (PMID 39527497, 2024). "Serum FABP‐4 levels were significantly higher in patients with hypothyroidism compared to the control group (p = 0.002), and serum FABP‐4 level in males was higher than it in females (p = 0.022)." (PMID 39527497, 2024). "In this study, we aimed to determine the serum levels of FABP4 in patients with hypothyroidism and compare them with those of the control group as well as their concentration correlation with the thyroid hormone panel, liver function tests and lipid profile." (PMID 39527497, 2024). "In the current study, we compared the difference in circulating FABP4 levels between 45 patients with hypothyroidism and 45 healthy controls." (PMID 39527497, 2024). "In our study, there was a notable increase in serum FABP‐4 concentration among hypothyroidism subjects." (PMID 39527497, 2024). "We displayed that patients with hypothyroidism were presented with higher serum FABP4 levels compared to the control group." (PMID 39527497, 2024). "In contrast, in a previous study, an elevation in the concentration of FABP4 has been observed in individuals with subclinical and overt hypothyroidism." (PMID 39527497, 2024). "This study aimed to evaluate serum FABP‐4 levels in hypothyroidism patients in comparison with a control group." (PMID 39527497, 2024). "Serum FABP4 levels were significantly higher in patients with subclinical and overt hypothyroidism than healthy controls (HCs) (P = 0.044 and P = 0.014, respectively)." (PMID 31651119, 2019). "In the current study, we aimed to evaluate the effect of FABP4 on the development of CVD in patients with hypothyroidism." (PMID 31651119, 2019). "In patients with subclinical and overt hypothyroidism, the level of FABP4 increases and this increase is correlated with the increase in TSH level." (PMID 31651119, 2019). "Screening for Hypothyroidism, using FABP4 levels is a novel method which may be used to detect other hypothyroidism‐related diseases." (PMID 39527497, 2024). "Moreover, in our current study, serum levels of FABP4 were higher in males with hypothyroidism than it in females with hypothyroidism, and there was a significantly positive correlation between serum FABP4 and Weight." (PMID 39527497, 2024). "Increased serum FABP4 levels were not closely associated with thyroid hormones panel, liver function tests or lipid profile in patients with hypothyroidism." (PMID 39527497, 2024). "This study explained the possible capacity that FABP4 could play as a potential biomarker for the prediction and prompt detection of patients with hypothyroidism." (PMID 39527497, 2024). "Another study, including an equal number of subclinical hypothyroid, overt hypothyroid, and healthy patients (n = 40 in each group), found that in patients with subclinical and overt hypothyroidism, the level of FABP4 was high, and the elevation closely correlated with high TSH." (PMID 38731797, 2024). "Serum FABP4 levels were higher in patients with Hypothyroidism than in HC (p = 0.002)." (PMID 39527497, 2024).
hypothyroidism (continued). "Moreover, serum FABP4 levels were higher in males with hypothyroidism than in females (p = 0.022)." (PMID 39527497, 2024). "The aim of this study is to evaluate the relationship between serum fatty acid binding protein 4 (FABP4) levels and carotid intima media thickness (CIMT) in patients with hypothyroidism." (PMID 31651119, 2019). "In the hypothyroidism group, there was a weak correlation but no significance FABP4 with TG, total‐Cho, VLDL, LDL and HDL." (PMID 39527497, 2024). "We documented that an increased level of FABP4 in patients with hypothyroidism was not correlated with lipid profile and liver function tests." (PMID 39527497, 2024). "There was a weak correlation but no significance between FABP4 and thyroid hormones panel in hypothyroidism and healthy control groups." (PMID 39527497, 2024). "There was a weak correlation but no significance between FABP4 and liver function in hypothyroidism and healthy control groups." (PMID 39527497, 2024). "In hypothyroidism group, there was a significantly negative correlation FABP4 with age (r = −0.356, p = 0.016) and a significantly positive correlation FABP4 with weight (r = 0.301, p = 0.044)." (PMID 39527497, 2024). "In addition, we reported that increased serum levels of FABP4 in patients with hypothyroidism were not correlated with thyroid hormones panel." (PMID 39527497, 2024). "Additionally, we noted that increased serum levels of FABP4 in patients with hypothyroidism were not correlated with LFT and lipid profile." (PMID 39527497, 2024).
invasive breast carcinoma (3 papers, 2017 to 2025). A carcinoma that infiltrates the breast parenchyma. "Further, in invasive breast cancer, the loss of FABP4 expression is associated with a higher risk of progression." (PMID 31803141, 2019). "In patients with invasive breast cancer, most tumor cells were FABP4-negative." (PMID 40106183, 2025).
kidney stone (3 papers, 2022 to 2025). "In lipid metabolism, fatty acid binding protein 4 (FABP4) plays a protective role against kidney stone formation, with knockdown of FABP4 accelerating stone development." (PMID 39854602, 2025). "In addition, the formation of kidney stones was significantly increased in a mouse model after the lipid metabolism-related protein fatty acid binding protein 4 (FABP4) was knocked out." (PMID 36225869, 2022).
lupus nephritis (3 papers, 2018 to 2026). Glomerulonephritis in the context of systemic lupus erythematosus. "In human normal kidney tissue, FABP4 is mainly expressed in perianal blood vessels, whereas FABP4 is highly expressed in glomerular CD68-positive macrophages and CD34-positive endothelial cells in lupus nephritis, affecting urine protein and renal function." (PMID 30135658, 2018). "Previous study has reported that FABP4 was detected in some tubular cells in patients with stage IV lupus nephritis, not in normal kidneys, suggested that the increase of FABP4 in renal tubular cells might be related with renal dysfunction." (PMID 30135658, 2018).
macrosomia (3 papers, 2021 to 2025). "• An increased mRNA expression of placental FABP4 in macrosomia than in control group (p < 0.05)." (PMID 37628833, 2023).
meningioma (3 papers, 2022 to 2024). A generally slow growing tumor attached to the dura mater. "We previously found that high plasma GFAP was associated with GBM, low GFAP and high FABP4 were associated with meningiomas and low GFAP and low FABP4 were associated with astrocytomas." (PMID 38879494, 2024). "High plasma GFAP concentration was associated with GBM, low GFAP and high FABP4 were associated with meningiomas, and low GFAP and low FABP4 were associated with astrocytomas and oligodendrogliomas." (PMID 38879494, 2024). "FABP4 has a role in carcinogenesis in meningiomas by stimulating cell proliferation in a cell type-independent way." (PMID 36959545, 2023). "Another study analyzed FABP4 expression in a cohort of paraffin-embedded meningioma specimens by immunohistochemistry and double immunofluorescence analyses." (PMID 36959545, 2023). "FABP4 could have a role in carcinogenesis in meningiomas by stimulating cell proliferation in a cell type-independent way." (PMID 38879494, 2024). "A combination of FABP4 immunostaining with histopathologic grading might provide a more accurate prediction of the biological behavior of meningiomas than histopathologic grading alone." (PMID 36959545, 2023). "FABP4 is expressed in vascular endothelial cells of meningiomas, especially anaplastic meningiomas, and may serve as a potential marker." (PMID 36060264, 2022). "All patients with meningiomas had GFAP < 226 pg/mL and FABP4 > 7,736 pg/mL." (PMID 38879494, 2024).
metastatic cancers (3 papers, 2021 to 2023). A carcinoma which has spread from the original site of growth to another anatomic site. "Numerous studies have shown that FABP4 is a poor prognostic factor in metastatic cancers such as colon, cervical and breast cancers." (PMID 35479956, 2022). "In addition, FABP4 plays a malignant role in metastatic cancers, especially in THCA." (PMID 36418670, 2023). "Upregulation of several fatty acid transporter genes, such as FABP4 and CD36, has been reported in metastatic cancer." (PMID 37849907, 2021).
morbid obesity (3 papers, 2017 to 2023). An excess of body weight, normally defined as an individual with a body mass index greater than 35 or a body weight greater than one hundred percent of ideal body weight. "Thus, it is not surprising that we did not observe any alternations in FABP4 expression in different depots of adipose tissue, since examined patients with morbid obesity were sensitive to insulin." (PMID 29335416, 2018). "In our study, there was no change in FABP4 protein expression in SAT and VAT in patients with morbid obesity compared to the lean controls." (PMID 29335416, 2018).
Myocardial fibrosis (3 papers, 2022 to 2025). "FABP4 is considered a biomarker for cardiac fibrosis, while the FABP4 level improved in cardiac fibrosis patients may speculate the association of FABP4 in myocardial fibrosis and the advancement of cardiac fibrosis." (PMID 36311201, 2022). "Moreover, a disturbance in lipid metabolism can accelerate the formation of FABP4+ fibroblasts and accelerate myocardial fibrosis." (PMID 39198543, 2024). "Thus, partial elimination of CD34+ cells leads to a significant reduction in FABP4+ fibroblasts within the heart, resulting in decreased TG content, reduced myocardial fibrosis, and improved cardiac function." (PMID 39198543, 2024).
non-small cell lung carcinoma (3 papers, 2020 to 2024). A group of at least three distinct histological types of lung cancer, including non-small cell squamous cell carcinoma, adenocarcinoma, and large cell carcinoma. "High expression of FABP3, at both mRNA and protein levels, in conjunction with FABP4, indicate poor prognosis in patients with non-small cell lung cancer (NSCLC), suggesting an oncogenic role of this chaperone." (PMID 32856199, 2020). "In non-small-cell lung cancer (NSCLC), both FABP3 and FABP4 are upregulated and positively correlated with the advanced tumour node metastasis stage (TNM) across matched cancerous and non-cancerous tissue from 30 patients." (PMID 38610991, 2024).
obstructive sleep apnea (3 papers, 2014 to 2021). "In humans, elevated circulating FABP-4 levels are associated with obstructive sleep apnea and significantly correlate with hypoxemia." (PMID 33535425, 2021). "Circulating FABP4 level was associated with increased LV mass in overweight and obese women and in patients with obstructive sleep apnea syndrome." (PMID 25142635, 2014).
peripheral vascular disease (3 papers, 2015 to 2024). Any disorder affecting blood flow through the veins or arteries outside of the heart. "FABP4 may be a useful biomarker for patients with stable peripheral vascular disease at risk of major cardiovascular problems, according to previous studies." (PMID 36432506, 2022).
pregnancy-induced hypertension (3 papers, 2018 to 2024). "Elevated levels of fatty acid binding protein 4 (FABP4) in the second trimester were associated with an increased risk of pregnancy-induced hypertension (PIH), demonstrating an AUC of 0.647." (PMID 39519218, 2024). "A study focused on overweight patients showed that serum FABP4 concentrations in the second trimester were associated with subsequent development of GH/PE (refer to pregnancy induced hypertension (PIH) in the study)." (PMID 29394285, 2018). "• Similar FABP4 levels in PE and control groups.• An inverse correlation between FABP4 levels and weight gain during pregnancy in women with pregnancy-induced hypertension (p = 0.02)." (PMID 37628833, 2023).
renal cell carcinoma (3 papers, 2014 to 2022). "Fabp4, Gsn, Il6st, and Ly6e, were associated with nephritis and Col18a1, Prom1, and Scd1 with renal cell carcinoma." (PMID 25409434, 2014). "This suggests that FABP4 has tumor suppressor effects in lung and renal cell carcinoma." (PMID 36532833, 2022).
retinal vein occlusion (3 papers, 2021 to 2024). An occlusion of the retinal vein. "The main objective of current study was to identify the fatty acid-binding protein 4 (FABP4) expressed in both adipocytes and macrophages in vitreous fluid from patients with retinal vein occlusion (RVO)." (PMID 33503066, 2021). "Since several of these diseases related to FABP4 are also well-known as key risk factors for various RVDs including proliferative DR (PDR), retinal vein occlusion (RVO), and AMD, it has been rationally suggested that FABP4 is involved in the pathogenesis of RVDs." (PMID 39062961, 2024).
rhabdomyolysis (3 papers, 2018 to 2023). Necrosis or disintegration of skeletal muscle often followed by myoglobinuria. "Pharmacological inhibition of fatty acid-binding protein 4 reduces renal tubular epithelial cell damage induced by rhabdomyolysis via inhibiting ERS." (PMID 37173347, 2023). "In the study, we further investigated the effect of FABP4 in a murine model of glycerol injection-induced rhabdomyolysis." (PMID 30135658, 2018). "Collectively, these data demonstrated that pharmacological inhibition of FABP4 contributed to ameliorate renal ER-stress and inflammation in tubular cells in rhabdomyolysis-induced AKI." (PMID 30135658, 2018). "We also examined the protective effects of FABP4 inhibitor on the renal proximal tubular cell, the main injury site of rhabdomyolysis-induced AKI, using an in vitro myoglobin stimulation." (PMID 30135658, 2018). "Anyway, further detailed studies are needed to determine whether macrophage FABP4 expression was involved in rhabdomyolysis related kidney injury." (PMID 30135658, 2018). "However, the potential of FABP4 as drug target for the treatment of rhabdomyolysis-induced AKI was still unknown." (PMID 30135658, 2018). "Male C57BL/6 mice were injected by glycerol to create a model of rhabdomyolysis-induced AKI as indicated, and FABP4 protein and mRNA expression was examined." (PMID 30135658, 2018).
serous carcinoma (3 papers, 2017 to 2021). "FABP4 expression was highest in vessels of low-grade serous carcinoma, and in the stromal compartment of advanced serous carcinoma, challenging the question whether tumour endothelial FABP4 expression is required for tumour progression." (PMID 27568980, 2017).
Simpson-Golabi-Behmel syndrome (3 papers, 2022 to 2025). Simpson-Golabi-Behmel syndrome is a rare X-linked multiple congenital anomalies syndrome, characterized by pre- and postnatal overgrowth, distinctive craniofacial features, variable congenital malformations, organomegaly and an increased tumor risk. "Kranendonk and colleagues were amongst the earliest groups to characterize human adipocyte EVs (defined as adiponectin and fatty-acid binding protein 4-positive EVs), isolated from the Human Simpson Golabi Behmel Syndrome (SGBS) cell line." (PMID 40497934, 2025).